IFIT2 (interferon induced protein with tetratricopeptide repeats 2)
Diseases named in the same sentence as IFIT2 in open-access papers (continued):
Sharing a sentence is not in itself a finding about the gene and the disease.
esophageal cancer (4 papers, 2022 to 2025). A primary or metastatic malignant neoplasm involving the esophagus. "The findings demonstrate that IFIT2 expression is linked to the suppression of the oxidative phosphorylation pathway in tissues from esophageal cancer." (PMID 36386128, 2022). "We also revealed that, in human esophageal cancer tissues, the PD-L1 expression level was significantly and inversely associated with IFIT2 expression level (χ2 = 4.980, P = 0.0256)." (PMID 35107757, 2022). "METTL3 and IFIT2, which may serve as prognostic or diagnostic indicators for esophageal cancer, also offer fresh evidence in favor of immunotherapy and customized treatment for ESCC patients." (PMID 36386128, 2022). "High IFIT2 expression levels were also correlated with better overall survival in esophageal cancer patients compared to those with low IFIT2 expression." (PMID 40564154, 2025). "The results of CCK-8 and cloning experiments showed that IFIT2 overexpression attenuated the proliferation of esophageal cancer cells." (PMID 36386128, 2022). "In our present study, we established the cellular model of stable knockdown IFIT2 expression in human esophageal cancer cell lines, Eca-109 and TE-1, according to the methods we have used and described in our previous report." (PMID 35107757, 2022). "In our present work, the cellular studies results showed that in human esophageal cancer cells, decreased IFIT2 expression significantly increased the cellular ability of viability, invasion and migration." (PMID 35107757, 2022). "Collectively, our current findings provided a novel mechanism underlying the effects of PD-L1 on EMT of cancers, showing that STAT1/IFIT2 signaling pathway was required in PD-L1-mediated EMT in human esophageal cancer." (PMID 35107757, 2022). "Decreased IFIT2 expression significantly increased the cellular abilities of viability, invasion and migration by using RNAi method in human esophageal cancer cells." (PMID 35107757, 2022). "In TCGA esophageal cancer samples, IFIT2 gene expression and pathway enrichment were correlated by GSEA enrichment analysis." (PMID 36386128, 2022). "To further investigate the relationship between METTL3 and IFIT2 in the tumorigenesis of esophageal cancer, we knocked down IFIT2 in KYSE150 cells, accompanied by METTL3 knockdown." (PMID 36386128, 2022). "Rescue experiments in PD-L1 knockdown cells further confirmed that STAT1/IFIT2 pathway was involved in the PD-L1 mediated EMT of esophageal cancer cells." (PMID 35107757, 2022). "Our present findings provided a novel mechanism underlying the effects of PD-L1 on EMT of cancer cells, showing that STAT1/IFIT2 signaling pathway was required in PD-L1-mediated EMT in human esophageal cancer." (PMID 35107757, 2022). "In this study, we demonstrate that METTL3 regulates esophageal cancer proliferation, invasion, and immunity via the downstream target IFIT2." (PMID 36386128, 2022). "ROC curve analysis showed that the risk model constructed by the expression and prognosis of IFIT2 and METTL3 in esophageal cancer patients was closely related to the prognosis survival of more than 3 years (AUC = 0.77)." (PMID 36386128, 2022). "The STAT1/IFIT2 signal pathway was activated when PD-L1 was knockdown in human esophageal cancer cells." (PMID 35107757, 2022). "The IFIT2 expression level in esophageal cancer tissues significantly correlates with patient’s gender (P = 0.002), but not other parameters, such as age, tumor size, T stage, lymphatic metastasis, distant metastasis or TNM stage." (PMID 35107757, 2022). "Herein, we also aimed to examine the expression pattern and the clinical significance of IFIT2 in human esophageal cancer tissues." (PMID 35107757, 2022). "Our present work reveals a novel mechanism of how PD-L1 regulates EMT of cancer cells, namely STAT1/IFIT2 signal pathway is required in PD-L1 mediated EMT in human esophageal cancer." (PMID 35107757, 2022).
esophageal cancer (continued). "METTL3 could regulate esophageal cancer proliferation, invasion and immunity via the downstream target IFIT2." (PMID 37598390, 2023). "Therefore, it is necessary to further explore how PD-L1 reflects the IFIT2 expression in human esophageal cancer cells needs to be studied." (PMID 35107757, 2022). "The METTL3 downstream target gene IFIT2 was identified in esophageal cancer cells using MeRIP-seq." (PMID 36386128, 2022). "Moreover, we further investigated the cellular functions of esophageal cancer cells after IFIT2 knockdown expression." (PMID 35107757, 2022). "In conclusion, IFIT2 and METTL3 may serve as targets for immunotherapy in addition to being potential pathogenic factors in esophageal cancer development." (PMID 36386128, 2022). "Therefore, we investigated the correlation of METTL3 and IFIT2 expression with immune cells in esophageal cancer." (PMID 36386128, 2022). "Moreover, the luciferase reporter assay also confirmed that in esophageal cancer cells, the promoter region of IFIT2 (-3K~-1K) remains more active in PD-L1 knockdown expression cells compared with controls." (PMID 35107757, 2022). "Decreased IFIT2 expression in esophageal cancer tissues significantly correlated with EMT status, and could be used as an independent prognostic predictor for the patients." (PMID 35107757, 2022). "We then characterized the expression relationship of IFIT2 with METTL3 in esophageal cancer cells." (PMID 36386128, 2022). "In our present study, we found that modification of PD-L1 expression could significantly regulate the STAT1/IFIT2 signaling pathway in human esophageal cancer cells." (PMID 35107757, 2022). "Additionally, the immune response during the development of esophageal cancer may be mediated by METTL3 and IFIT2, which would explain why patients with esophageal cancer have a poor prognosis." (PMID 36386128, 2022). "Herein, we further investigated the clinical significance and biological role of IFIT2 in human esophageal cancer, and confirmed that STAT1/IFIT2 pathway was involved in the PD-L1-mediated EMT of esophageal cancer cells." (PMID 35107757, 2022). "The expression levels of IFIT2 and EMT markers in esophageal cancer tissues were examined by immunohistochemical staining." (PMID 35107757, 2022). "In addition, the retrospective study by examining the IFIT2 expression in human esophageal cancer tissues also demonstrated that decreased IFIT2 expression could be used as an independent prognostic predictor for esophageal cancer patients." (PMID 35107757, 2022).
gallbladder cancer (4 papers, 2018 to 2022). "For example, interferon-induced protein with tetratricopeptide repeats 2 (IFIT2) can inhibit the invasion and metastasis of gallbladder carcinoma." (PMID 36104718, 2022). "The tumor suppressor promyelocytic leukemia zinc-finger protein (PLZF) was reported to increase expression of IFIT2 in gallbladder cancer." (PMID 30875792, 2019).
HIV-1 infection (4 papers, 2014 to 2023). The type species of lentivirus and the etiologic agent of acquired immunodeficiency syndrome (AIDS). "We also noted that HIV-1 infection induces a prominent antiviral state in early/mid-gestation HCs, characterized by transcription and secretion of IFN-α and significantly elevated transcription of the RLRs, STAT1, STAT5, ISG15, OAS1, IFIT1, IFIT2, IFIT3, and Viperin." (PMID 34432853, 2021). "As previously shown, HIV-1 infection of primary CD4+ T cells failed to induce or very weakly induced (in cells from donor I) type I IFN production and the IFN-responsive genes ISG15, IFIT1, and IFIT2." (PMID 37922361, 2023).
intrahepatic cholangiocarcinoma (4 papers, 2022 to 2026). A carcinoma that arises from the intrahepatic bile duct epithelium in any site of the intrahepatic biliary tree. "In addition, YTHDF1 and YTHDF2 facilitate the advancement of intrahepatic cholangiocarcinoma (ICC) through increasing EGFR mRNA translation and IFIT2 mRNA decay, respectively." (PMID 36999016, 2023).
leukemia (4 papers, 2014 to 2025). A malignant (clonal) hematologic disorder, involving hematopoietic stem cells and characterized by the presence of primitive or atypical myeloid or lymphoid cells in the bone marrow and the blood. "IFIT2 can enhance the apoptotic effect of curcumin-induced leukemia cells." (PMID 40454173, 2025).
lupus (4 papers, 2020 to 2023). "Recent evidences have demonstrated that IFIT2 and IFIT3 may contribute to the pathogenesis of autoimmune diseases, such as systemic lupus erythematosus, sjögren’s syndrome and pemphigus." (PMID 32793290, 2020).
glioma (3 papers, 2005 to 2024). A benign or malignant brain and spinal cord tumor that arises from glial cells (astrocytes, oligodendrocytes, ependymal cells). "In this study on glioma cells, the activation of numerous interferon-induced proteins (such as IFIT1, IFIT2, IFI27, IFITM1, IFITM2, and G1P2) lends support to this mechanism of pathogenicity." (PMID 15829208, 2005).
ovarian carcinoma (3 papers, 2019 to 2022). A malignant neoplasm originating from the surface ovarian epithelium. "IFIT2 is significantly overexpressed in ovarian cancer stem cells, indicating its potential role in drug resistance in ovarian cancer." (PMID 35810383, 2022). "Accordingly, increased resistance to carboplatin has been reported after upregulation of miR‐193b by directly targeting CRIM1 and IFIT2 in ovarian cancer cells." (PMID 33072537, 2020). "In human ovarian cancer cells, the down-regulation of IFIT2 was regulated by activation of the Ras/MEK signaling pathway." (PMID 30875792, 2019).
Sepsis (3 papers, 2018 to 2023). Sepsis is defined as life-threatening organ dysfunction caused by a dysregulated host response to infection. "Because renal insufficiency and kidney fungal burden correlate with lethality in this sepsis model, we evaluated kidneys of WT and IFIT2 KO mice." (PMID 29666281, 2018). "IFIT1 and IFIT2, although known for antiviral properties, were broadly expressed, suggesting their roles extend beyond viral defense to broader immune regulatory functions in sepsis." (PMID 38239341, 2023). "Importantly, we identified six critical genes, including CS, CYP1B1, FLVCR1, IFIT2, MAPK14, and PID1, which showed favorable diagnostic value in screening sepsis samples from normal samples." (PMID 37398680, 2023). "IFIT1 and IFIT2, known for their antiviral properties, exhibited broad expression across various cell types, indicating their involvement may transcend beyond viral defense mechanisms to broader immune regulatory roles within the context of sepsis." (PMID 38239341, 2023). "We observed an upregulation in the expression of IFI44, IFIH1, IFIT1, IFIT2, and RSAD2 in lung tissues from animals suffering from sepsis." (PMID 38239341, 2023). "Using bioinformatics techniques, we identified PID1, CS, CYP1B1, FLVCR1, IFIT2, and MAPK14 as six MRGs that are essential in the course of sepsis." (PMID 37398680, 2023). "Finally, we collected 15 sepsis samples and 15 normal samples and performed RT-PCR to examine the expression of CS, CYP1B1, FLVCR1, IFIT2, MAPK14, and PID1 in our cohort, which further confirmed our previous findings." (PMID 37398680, 2023). "We found that the expression of MAPK14 and CYP1B1 was distinctly increased in sepsis samples compared with normal samples, while the expression of PID1, CS, FLVCR1, and IFIT2 was distinctly decreased in sepsis samples compared with normal samples." (PMID 37398680, 2023). "Additionally, ZBP1, XAF1, IFI44L, SOCS1, and PARP14 were notably high in HighPANscore cells, aligning with our observations of upregulated expression of IFI44, IFIH1, IFIT1, IFIT2, and RSAD2 in lung tissues from sepsis-induced animal models." (PMID 38239341, 2023).
ZIKV infection (3 papers, 2017 to 2022). "In U87MG cells, TMEM120A overexpression increased the transcription of IL6, IL8, and IFIT2 to a similar level as STING overexpression induced after ZIKV infection." (PMID 35013224, 2022). "The IFNβ and its downstream ISGs, including IFIT1 and IFIT2, were induced by ZIKV infection." (PMID 28373913, 2017). "During ZIKV infection we observed a reduction of IFNL1, IFIT1, and IFIT2, but not IFNB, IFIT3, and ISG15 transcription in the absence of DNA-PKcs." (PMID 36311766, 2022). "Similarly, in RPE cells, where ZIKV infection does not induce IFNL1 transcription, the absence of DNA-PKcs decreased IFNB and IFIT2, but not ISG15 transcription." (PMID 36311766, 2022).
colitis (2 papers, 2017 to 2025). Inflammation of the colon. "This was accompanied by a prominent increase in colonic mRNA of the proinflammatory cytokines Il‐1β, Tnfa, and Il‐6 as well as the interferon‐stimulated gene, Ifit2, in mice with colitis compared to the healthy controls." (PMID 40018982, 2025). "After induction of acute colitis with DSS, we found with EdgeR and CuffDiff2 analyses that the expression of 11 genes (Clps, Ddx60, Fgb, Fgg, Ifi44, Ifit2, Isg15, Itih3, Itih4, Oas3 and Usp18), which are involved in antimicrobial response, was increased in MMP-9−/− compared to WT mice." (PMID 28561062, 2017).
ischemic cardiomyopathy (2 papers, 2021 to 2024). Ischemic cardiomyopathy is a cardiomyopathy in which a weakness in the muscle of the heart due to inadequate oxygen delivery to the myocardium with coronary artery disease being the most common cause. "IFIT2 has been identified as a potential biomarker of ischemic cardiomyopathy in human and rat heart tissue samples, and it has been found to be highly expressed in HF patients with pulmonary arterial hypertension." (PMID 38355637, 2024). "Three interferon stimulated genes (IFIT2, IFIT3 and IFI44L), as well as key pathways, have been identified as potential biomarkers and therapeutic targets for ischemic cardiomyopathy, and their alternations or mutations have been proven to be strongly linked to cardiac disorders." (PMID 34884921, 2021).
neuroblastoma (2 papers, 2012 to 2023). Neuroblastoma (NB) is the most common solid, extracranial childhood tumor. "In mouse neuroblastoma cells, IFIT2 silencing by siRNA increases the number of viral RNA copies in a time-dependent manner and Ifit2-/- mice have an increased mortality after RABV infection." (PMID 37515100, 2023). "For example, Ifit2 was not required for mediating the anti-VSV effect of IFN in mouse embryonic fibroblasts, in primary fetal neurons or in Ifit2-ablated neuroblastoma cells (data not shown), results that are not surprising given the strong tissue-specificity of Ifit2 action observed in vivo." (PMID 22615570, 2012).
schizophrenia (2 papers, 2022 to 2025). A major psychotic disorder characterized by abnormalities in the perception or expression of reality. "In conclusion, our findings illustrate an epigenetic mechanism by which upregulation of lncRNA RP5-998N21.4 underlies the development of schizophrenia via the enhancement of IFIT2- and IFIT3-mediated immune defense responses through activation of STAT1 signaling pathways." (PMID 35232977, 2022). "We then observed significant overlap (three overlapping genes (IFIT2, IFIT3, and ANXA3; OR = 77.4, P = 7.4e−5) between RP5-998N21.4OE-induced DEGs in SK-N-SH cells and RP5-998N21.4-coexpressed schizophrenia-associated DEGs in twin subjects." (PMID 35232977, 2022). "Although our studies demonstrate the involvement of RP5-998N21.4 in the development of schizophrenia through the enhancement of IFIT2- and/or IFIT3-mediated immune defense response pathways, it is currently unclear how RP5-998N21.4 influences synapse morphology and function." (PMID 35232977, 2022). "Collectively, these results indicate that RP5-998N21.4 might regulate immune defense-related pathways by promoting the transcription of IFIT2, IFIT3, or ANXA3, which are involved in the pathophysiology of schizophrenia." (PMID 35232977, 2022).
triple-negative breast carcinoma (2 papers, 2020 to 2022). An invasive breast carcinoma which is negative for expression of estrogen receptor (ER), progesterone receptor (PR), and human epidermal growth factor receptor 2 (HER2). "Baicalein inhibits the expression of stem cell markers CD44highCD24low and octamer-binding transcription factors (OCT)-3 and 4 in triple negative breast cancer cell lines, through the inhibition of interferon-induced protein with tetratricopeptide repeats 2 (IFIT2)." (PMID 32471061, 2020).
tuberculosis (2 papers, 2019 to 2025). A chronic, recurrent infection caused by the bacterium Mycobacterium tuberculosis. "KEGG pathway analysis supported these findings, indicating significant impacts on these pathways and inhibition of the tuberculosis pathway, highlighting IFIT2’s role in enhancing immune responses to eliminate M. tb." (PMID 40463504, 2025). "Additionally, we observed from our Signaling Impact analysis that the tuberculosis pathway was inhibited confirming the downstream contributing factors to the antimycobacterial activity of IFIT2." (PMID 40463504, 2025).
acute myeloid leukemia (1 paper, 2025). Acute myeloid leukemia (AML) is a group of neoplasms arising from precursor cells committed to the myeloid cell-line differentiation. "IFIT1, IFIT2, IFIT3, and IFIT5 are overexpressed in acute myeloid leukemia (AML) patients, with higher levels of IFIT2, IFIT3, and IFIT5 predicting poor prognosis." (PMID 41048997, 2025).
apical periodontitis (1 paper, 2023). "Importantly, we demonstrated that miR-199a-5p effectively promoted the osteogenic activity of hSCAPs both in vitro and in vivo via directly regulating IFIT2 expression, which suggests its possibility to be potentially utilized to facilitate bone regeneration during apical periodontitis." (PMID 37063854, 2023).
bacterial sepsis (1 paper, 2023). "Similar to bacterial sepsis, IFIT2 knockout mice exhibited increased survival when challenged against a systemic Candida albicans infection." (PMID 36851555, 2023).
cervical carcinoma (1 paper, 2023). A carcinoma arising from either the exocervical squamous epithelium or the endocervical glandular epithelium. "IFITs suppress RSV infection in human cervical carcinoma cells as shown by overexpression of IFIT1, IFIT2 or IFIT3 individually." (PMID 37515100, 2023).
chronic mucocutaneous candidiasis (1 paper, 2018). "Notably, the levels of IL-17, a cytokine that has been shown to be essential for protective immunity during chronic mucocutaneous candidiasis, were similar in IFIT2 KO and WT mice and actually lower than those in uninfected mice." (PMID 29666281, 2018).
chronic viral hepatitis (1 paper, 2025). "In line with a constitutive ISG expression in NK cells, we also showed that the expression of IFITM3, IRF1, IFIT2 and ISG20 are refractory to IFN stimulation in vitro in NK cells that were obtained from patients with HD and chronic viral hepatitis." (PMID 40837234, 2025).
clear cell renal cell carcinoma (1 paper, 2025). "Similarly, in patients with clear cell renal cell carcinoma (ccRCC), higher IFIT2 expression correlated with improved overall survival, compared to patients with lower IFIT2 expression." (PMID 40564154, 2025).
colon cancer (1 paper, 2017). "Importantly, this is the first report showing that IFIT1 and IFIT2 are negatively regulated by Wnt signaling in colon cancer." (PMID 29245969, 2017).
colorectal adenoma (1 paper, 2017). An adenoma that arises from the colon or rectum. "In addition, two datasets (GSE4183 and GSE8671) revealed that expression levels of IFIT1 and IFIT2 were also down-regulated in colorectal adenoma tissues compared with normal tissues." (PMID 29245969, 2017).